IGFBP2 (insulin like growth factor binding protein 2)
Diseases named in the same sentence as IGFBP2 in open-access papers (continued):
Sharing a sentence is not in itself a finding about the gene and the disease.
Encephalopathy (1 paper, 2021). Encephalopathy is a term that means brain disease, damage, or malfunction. "The ROC curve analysis indicated that the area under the curve and the optimal serum IGFBP2 cutoff level were 0.7917 and 3585 pg/mL for association with encephalopathy had a sensitivity of 91.7% and a specificity of 70%." (PMID 33641616, 2021). "Specifically, our analyses suggest that patients with serum IGFBP2 levels above 3585 pg/mL were at the high risk for encephalopathy." (PMID 33641616, 2021). "A serum IGFBP2 level above 3585 pg/mL was associated with a high risk of encephalopathy." (PMID 33641616, 2021). "The serum IGFBP2 levels in patients with encephalopathy showed a significant and sharp increase with the progression of HUS (p<.05) whereas there was no increase in serum IGFBP2 levels with the progression of disease in patients with mild HUS." (PMID 33641616, 2021). "Among the patients with HUS, serum IGFBP2 levels were significantly higher in those with encephalopathy than in those with mild HUS (p<.05)." (PMID 33641616, 2021). "Furthermore, serum IGFBP2 level was useful in predicting the development of encephalopathy." (PMID 33641616, 2021). "Based on this serum IGFBP2 cutoff level, the odds ratio for HUS-related encephalopathy was 25.7 (95% confidence interval, 2.4–307.3), and the likelihood ratio was 3.056." (PMID 33641616, 2021). "Serum IGFBP2 levels were measured during the pre-HUS phase in six patients with HUS, including two patients with mild group and four patients with encephalopathy group." (PMID 33641616, 2021). "In the present study, serum IGFBP2 levels were significantly higher in patients with encephalopathy than in those without encephalopathy." (PMID 33641616, 2021). "Serum IGFBP2 levels were significantly higher in patients with encephalopathy than in those without encephalopathy, which included those with severe and mild group (median, 2395 pg/mL; range, 802–4180 pg/mL) (p<.05)." (PMID 33641616, 2021). "Additionally, serum IGFBP2 levels were significantly higher in patients with encephalopathy than in those without encephalopathy." (PMID 33641616, 2021).
endometriosis (1 paper, 2026). The growth of functional endometrial tissue in anatomic sites outside the uterine body. "The findings of the present study revealed for the first time, to the best of our knowledge, that PPARα and IGFBP2 are downregulated in endometriosis-affected ovaries and are negatively associated with senescence." (PMID 41170754, 2026). "The present study assessed whether rapamycin, a senescence inhibitor, ameliorates endometriosis-associated infertility by upregulating peroxisome proliferator-activated receptor α (PPARα) and insulin-like growth factor-binding protein 2 (IGFBP2) expression." (PMID 41170754, 2026). "In summary, the results of the present study highlight that ROS-induced ovarian senescence contributed to endometriosis-related infertility, and rapamycin counteracted this process by activating the PPARα/IGFBP2 pathway." (PMID 41170754, 2026). "This indicated that the expression of PPARα and IGFBP2 in the ovaries of endometriosis mice was significantly decreased, and treatment with rapamycin activated PPARα and IGFBP2 expression." (PMID 41170754, 2026). "In endometriosis, reduced PPARα/IGFBP2 signaling may exacerbate oxidative stress-induced ovarian damage." (PMID 41170754, 2026). "Rapamycin treatment increased PPARα and IGFBP2 expression in ovarian tissues, suggesting that its therapeutic effect on endometriosis-related infertility may involve the PPARα/IGFBP2 pathway by mitigating cellular senescence." (PMID 41170754, 2026). "The present study demonstrated that elevated ROS in the peritoneal fluid of endometriosis mice contributed to ovarian senescence and impaired follicular development, whilst rapamycin treatment mitigated these effects by reducing oxidative stress and activating the PPARα/IGFBP2 pathway." (PMID 41170754, 2026). "Therefore, the present study aimed to assess whether downregulation of the PPARα/IGFBP2 pathway in senescent ovarian tissue impairs follicular development, and whether rapamycin can restore fertility in endometriosis by modulating this signaling axis." (PMID 41170754, 2026).
esophageal squamous cell carcinoma (1 paper, 2022). Esophageal squamous cell carcinoma (ESCC) is a type of esophageal carcinoma (EC) that can affect any part of the esophagus, but is usually located in the upper or middle third. "However, MT2A is highly expressed in esophageal squamous cell carcinoma (ESCC) cells and promotes ESCC cell migration and invasion by regulating the expression and secretion of IGFBP2, thus influencing the NFκB, Akt and Erk signaling pathways." (PMID 35642057, 2022).
fibrosarcoma (1 paper, 2007). A malignant mesenchymal fibroblastic neoplasm affecting the soft tissue and bone. "Golub-score analysis identified a relatively poor discriminatory signal of 200 genes for the fibrosarcomas, which regardless of high FDR contained several of the upregulated genes previously associated with fibrosarcoma, e.g. BMI1, H1F0, LEF1, RBM4, ITM2A, IGFBP2 and PTGS2." (PMID 17359542, 2007).
hypercortisolemia (1 paper, 2022). "At the metabolic level, the observed increased availability of IRS2, IGFBP2 and, to a lower extent, IRS1 after treatment suggested an elevated sensitivity to insulin in VAT under hypercortisolemia." (PMID 35737302, 2022).
Hyperkeratosis (1 paper, 2018). Hyperkeratosis is a histopathological term defining a thickened stratum corneum and may be present in many different skin conditions, with many possible overlaps. "Reduced IGFBP-1 and IGFBP-2 levels could increase free IGF-1, thereby promoting the development of papillomatosis and hyperkeratosis observed in AN." (PMID 29706998, 2018).
hypertensive renal disease (1 paper, 2026). "POLR2F, TNFRSF10B, and IGFBP2 were positively associated with all five diseases, with Mendelian randomization supporting genetic associations of POLR2F with CHD and IGFBP2 with hypertensive renal disease." (PMID 41559658, 2026).
Impaired glucose tolerance (1 paper, 2021). "Arafat and colleagues (2009) demonstrated that insulin increases IGFBP2 in 24 healthy subjects and 19 subjects with impaired glucose tolerance." (PMID 33498859, 2021).
injury (1 paper, 2025). Damage inflicted on the body as the direct or indirect result of an external force, with or without disruption of structural continuity. "In these cases, IGFBP-2 may be useful in predicting the risk of severe septic kidney injury." (PMID 40231291, 2025). "However, the results of MR suggest that there is no direct causal relationship between plasma IGFBP-2 levels and septic kidney injury." (PMID 40231291, 2025).
keloid (1 paper, 2025). An irregularly shaped, elevated mark on the skin caused by deposits of excessive amounts of collagen during wound healing. "The POSTN‐positive subset is associated with excessive ECM production in keloids, while the IGFBP2‐positive subset, more prevalent in normal skin, exhibits anti‐fibrotic characteristics." (PMID 39902627, 2025). "However, further investigation is warranted to fully understand the mechanisms underlying IGFBP2+ fibs and their dynamic changes throughout keloid pathogenesis." (PMID 39902627, 2025). "Both POSTN+ mesenchymal fibs and IGFBP2+ fibs were associated with the ECM in keloids." (PMID 39902627, 2025). "Overall, the low expression of IGFBP2+ fib in keloids suggests its role in pathological scar formation differs from other diseases." (PMID 39902627, 2025). "IGFBP2+ fibs are not only less prevalent in keloids but also display reduced collagen expression compared to other fibroblasts." (PMID 39902627, 2025). "Results showed a higher proportion of IGFBP2+/APOD+ cells in normal skin samples compared to the keloid group." (PMID 39902627, 2025). "We then investigated the effects of POSTN+ mesenchymal fibs and IGFBP2+ fibs on collagen expression in keloid fibroblasts." (PMID 39902627, 2025). "Our research not only revealed the ubiquity and activity of POSTN‐positive mesenchymal fibroblasts in keloids but also discovered the predominant role of IGFBP2‐positive fibroblasts in normal skin and their potential significance in the process of anti‐fibrotic therapy." (PMID 39902627, 2025). "Interestingly, we also found a lower proportion of IGFBP2+ fib in keloids, indicating a potentially overlooked subpopulation." (PMID 39902627, 2025). "IGFBP2+ fibs are distinguished by the expression of marker genes including IGFBP2, FGFBP2, OLFML2A, CPE, APOD, and SLC7A2, which are markedly upregulated in normal skin tissue relative to keloid tissue." (PMID 39902627, 2025). "This study has uncovered the cellular diversity and molecular mechanisms of keloids through single‐cell and ST analysis, identifying the key roles of POSTN‐positive and IGFBP2‐positive fibroblast subsets." (PMID 39902627, 2025). "Additionally, we found that both IGFBP2+ fibs and POSTN+ mesenchymal fibs display strong cellular communication signals with endothelial cells in both keloid and normal skin tissues." (PMID 39902627, 2025). "We then focused on comparing the expression differences of IGFBP2+ fib marker genes (IGFBP2, FGFBP2, OLFML2A, CPE, APOD, SLC7A2) between keloids and normal controls." (PMID 39902627, 2025).
macrosomia (1 paper, 2025). "IGFBP-2 and IGFBP-5 emerged as significant independent predictors of LGA birth in adjusted models (OR = 2.515 and 2.402, respectively; p < 0.001), consistent with prior studies linking first-trimester IGF-1 and IGF-1/IGFBP-1 ratios to macrosomia." (PMID 40943286, 2025).
membranous nephropathy (1 paper, 2022). "The levels of IGFBP2 expression in kidneys of cases with membranous nephropathy (MN) and type II–V LN were examined by immunohistochemistry (IHC) and immunofluorescence staining (IF)." (PMID 36008635, 2022).
mood disorder (1 paper, 2011). A cognitive disorder a disturbance in which the person's mood is hypothesized to be the main underlying feature. "Another couple of interesting genes was Igfbp6 and Igfbp2 which have been shown to be involved in mood disorders and therefore could also have relevance to drug addiction given the interrelationship between both psychopathological spectra." (PMID 21886580, 2011).
myeloma (1 paper, 2020). "In patient samples, the authors suggest that production of small, immature IGFBP2+ adipocytes is negatively correlated with disease progression- suggesting that myeloma inhibits the formation of these cells, or that these cells are somehow utilized during MM progression." (PMID 33680918, 2020).
myopia (1 paper, 2023). "Further analysis using an insulin microarray resulted that the levels of insulin and those related factors including IGF2, IGF-2R, IGF binding protein 1 (IGFBP-1), IGFBP-2, IGFBP-3, IGFBP-4 and IGFBP-6 were markedly increased in patients with pathogenic myopia as compared with the controls." (PMID 38203671, 2023).
oro-pharyngeal cancers (1 paper, 2015). "In p16 positive cancers, IGFBP2 expression was significantly reduced, suggesting that down-regulation of IGFBP2 expression is likely associated with HPV infection in oro-pharyngeal cancers." (PMID 26107517, 2015). "We have utilised publically available gene array datasets to assess the expression of IGFBP2 in oro-pharyngeal cancers." (PMID 26107517, 2015).
ovarian serous tumor (1 paper, 2005). A benign, borderline, or malignant epithelial tumor of the ovary characterized by the presence of neoplastic epithelial cells that, in well differentiated tumors, resemble the epithelial cells of the fallopian tube and, in poorly differentiated tumors, show anaplastic features. "Increasing expression of IGFBP2 with progression of ovarian serous tumors*." (PMID 15686601, 2005).
Pallister Killian syndrome (1 paper, 2014). "Among the differentially expressed genes, we identified several genes whose misexpression may be associated with the clinical phenotype of Pallister Killian syndrome such as downregulation of ZFPM2, GATA6 and SOX9, and overexpression of IGFBP2." (PMID 25329894, 2014).
paraganglioma (1 paper, 2022). A benign or malignant neoplasm arising from paraganglia located along the sympathetic or parasympathetic nerves. "We found that IGFBP2 was significantly upregulated in the ICD-CB subtype compared with the ICD-CC subtype in pheochromocytoma and paraganglioma (PCPG)." (PMID 36497433, 2022).
periodontitis (1 paper, 2025). An acute or chronic inflammatory process that affects the tissues that surround and support the teeth. "Previous studies have reported heterogeneity in gingival fibroblasts in periodontal tissues, with four subsets significantly altered in periodontitis: Fib 1.1 (CXCL1, CXCL2, CXCL13); Fib 1.2 (APCDD1, IGFBP2, MRPS6); Fib 1.3 (APOD, GSN, CFD); and Fib 1.4 (TIMP3, ASPN, COL11A1)." (PMID 40801798, 2025).
plaque psoriasis (1 paper, 2020). "In this report, we investigated the expression and function of IGFBP2 in senescent keratinocytes isolated from the skin of patients with plaque psoriasis." (PMID 32302288, 2020). "In this study, we describe for the first time the intracellular role of IGFBP2 in keratinocytes of skin affected by plaque psoriasis, known to be characterized by hyper-proliferation, impaired terminal differentiation and marked senescence changes." (PMID 32302288, 2020).
progeria (1 paper, 2022). "We are—to our knowledge—the first to mention IGFBP2, which is known as an age-related mortality marker, as a potential biomarker in progeria." (PMID 36289702, 2022). "Applying these stricter standards, three of the genes that are differentially expressed in aging and progeria (TFPI, STAT1, IGFBP2) appear to be associated with changes in protein expression." (PMID 36289702, 2022). "We are, to our knowledge, the first to report and stress these elevated IGFBP2 levels in progeria patients." (PMID 36289702, 2022). "We also present here the miRNAs and interactomes for the three genes connecting aging, the aging pathway, and progeria: WNT16 (hsa-mir-181a-5p), UCP2 (hsa-mir-26a-5p and hsa-mir-124-3p), and IGFBP2 (hsa-mir-124-3p, hsa-mir-126-3p, and hsa-mir-27b-3p)." (PMID 36289702, 2022). "Despite progeria being known as premature aging, only three genes of the aging pathway are differentially expressed in nonagenarians and progeria patients compared to the same group of healthy children: WNT16, UCP2, and IGFBP2." (PMID 36289702, 2022). "However, in progeria, IGFBP2 expression is considerably more elevated than in nonagenarians suggesting its role in both aging and progeria." (PMID 36289702, 2022).
rectal cancer (1 paper, 2019). A primary or metastatic malignant neoplasm that affects the rectum. "In addition to SMAD7 (P = 0.0005) and SMAD3 (P = 0.0003), several other genes or genetic regions (CYP2R1, CHAF1A, CREBBP, IL10, SNPs identified in genome-wide association studies (GWAS) to be associated with IGF levels, IGFBP2/IGFBP5, IGFBP3, and C-MYC region) were associated with rectal cancer." (PMID 31434255, 2019).
retinal degeneration (1 paper, 2023). Degeneration of the retina. "The results showed that proteins like CST3, C9, and ITM2B, among others, are associated with retinal degeneration while proteins such as COL1A2, IGFBP2, and AGT, among others, are associated with diabetic complications." (PMID 37884923, 2023).
retinal diseases (1 paper, 2014). "PDGF, VEGF, and IGFBP-2 have been shown to be involved in regular RPE functions or retinal diseases." (PMID 25136316, 2014).
rheumatic diseases (1 paper, 2021). "Previous studies reported that serum IGFBP2 levels were significantly elevated in patients with malignancies, rheumatic diseases, and kidney diseases and that serum IGFBP2 levels were closely related with disease severity." (PMID 33641616, 2021).
Sensory neuropathy (1 paper, 2023). Peripheral neuropathy affecting the sensory nerves. "Disrupting insulin signaling such as insulin-like growth factor-binding protein 2 (IGFBP2) in SCs, impairs myelination and induces a sensory neuropathy." (PMID 37594969, 2023).
septic shock (1 paper, 2023). Shock caused by infection; frequently caused by gram negative bacteria, although some cases have been caused by other bacteria, viruses, fungi, and protozoa; characterized by fever, chills, tachycardia, tachypnea, and hypotension. "When stratifying septic shock patients based on dialysis requirement, plasma IGFBP-2 levels were similar for both groups." (PMID 38137505, 2023).
Shock (1 paper, 2023). The state in which profound and widespread reduction of effective tissue perfusion leads first to reversible, and then if prolonged, to irreversible cellular injury. "However, comparing septic shock patients with and without dialysis showed similar plasma IGFBP-2 levels (p = 0.377)." (PMID 38137505, 2023).
skin aging (1 paper, 2022). The gradual irreversible changes in structure of skin that occur as a result of the passage of time.. "Both IGFBP2 and UCP2 are associated with miR-124, which has been shown to increase in senescent skin and upon UVB-irradiation (type B ultraviolet), indicating a possible role of miR-124 in UVB-induced skin aging." (PMID 36289702, 2022).
status epilepticus (1 paper, 2026). Status epilepticus is defined as a continuous seizure lasting more than 30 min, or two or more seizures without full recovery of consciousness between any of them. "Astrocytic Igfbp2 already showed a tendency toward upregulation at this early time point following KA‐induced status epilepticus." (PMID 41239819, 2026).
stomach adenocarcinoma (1 paper, 2023). "In stomach adenocarcinoma, IGFBP1 is upregulated, but IGFBP2 and IGFBP6 are downregulated." (PMID 37088808, 2023).
tauopathy (1 paper, 2018). Neurodegenerative disorders involving deposition of abnormal tau protein isoforms (tau proteins) in neurons and glial cells in the brain. "To further explore the role of IGFBP2 in tau pathobiology, we evaluated the expression of IGFBP2 in different human and mouse brain cell types and brain tissue from two transgenic mouse models: the P301L-tau model of tauopathy and TASTPM model of AD." (PMID 30061810, 2018). "To better understand how IGFBP-2 may impact AD pathogenesis, we further utilized gene expression data from transgenic mouse models of tauopathy and AD along with cell type specific expression from human and mouse to assess the relevance of IGFBP-2 dysregulation to neurodegeneration." (PMID 30061810, 2018).
thoracic aortic aneurysm (1 paper, 2023). An aneurysm formed in the wall of the proximal portion of the descending aorta proceeding from the arch of the aorta. "Further, an early activation of IGFBP2 represents a marker of early smooth muscle cell phenotype modulation in patients suffering from thoracic aortic aneurysms." (PMID 38379859, 2023).
thyroid cancer (1 paper, 2022). "In particular, HNRNPC, RBM15B, IGFBP2, and ELF3 were upregulated, while the other 12 genes were downregulated in thyroid cancer tissues." (PMID 36389678, 2022).
viral infections (1 paper, 2025). "Furthermore, anti-inflammatory properties of IGFBP2 during other viral infections were not studied." (PMID 40121473, 2025).
yang deficiency (1 paper, 2022). Yang deficiency is a concept from traditional Chinese medicine. "IGFBP2 was identified to be upregulated in this study and showed an induced level of 13.9- and 4.1-fold in Yang deficiency and Qi-yin deficiency patients, respectively." (PMID 35087594, 2022). "The IGFBP2 level could predict the mortality risk of HF, and the high upregulated level in Yang deficiency patients may suggest that these patients have an advanced stage of HF." (PMID 35087594, 2022).